AFP (alpha fetoprotein)
Diseases named in the same sentence as AFP in open-access papers (continued):
Sharing a sentence is not in itself a finding about the gene and the disease.
gastric cancer (continued). "In our case, the patient suffered from an early stage gastric cancer and serum AFP level was normal initially." (PMID 27631210, 2016). "Before our case discussion, we should explicate 2 conceptions, they are AFP-producing gastric cancer and hepatoid adenocarcinoma." (PMID 27631210, 2016). "Since the first report of AFP-producing gastric cancer in 1970, AFP-producing gastric cancer has been classified into four histological subtypes: hepatoid, yolk sac tumor, enteroblastic and common adenocarcinoma type." (PMID 27995033, 2016). "In this case, since no specific morphology was observed, we made the diagnosis of AFP-producing gastric cancer." (PMID 27995033, 2016). "Nonetheless, we conclude that relatively high levels of preoperative serum CA19-9, AFP, and CA125 within the normal limits are associated with poor prognosis of gastric cancer." (PMID 27533455, 2016). "Patient with α-Fetoprotein (AFP)-producing gastric cancer usually has a short survival time due to frequent hepatic and lymph node metastases." (PMID 25591731, 2015). "AFP-producing gastric cancer with a PVTT has an extremely poor prognosis, but long-term survival was achieved for this dismal condition by salvage surgery after chemotherapy." (PMID 25591731, 2015). "In some patients, an increase in AFP levels manifests liver metastasis with gastric cancer and the condition is termed as α-fetoprotein producing gastric cancer (AFPGC)." (PMID 24707212, 2014). "Zheng ZC, Wang SB, Cui XD, Xu HJ, Zhang PF: A study of the correlation of serum AFP and biological behaviors in gastric cancer.J Pract Oncol 1997, 11:45–47." (PMID 24083471, 2013). "Particularly, liver metastasis is a very important prognostic factor during the control of AFP-positive gastric cancer because 56.7% of AFPGC patients in our evaluation had liver metastasis." (PMID 24083471, 2013). "AFP-producing gastric cancer (AFPGC) has a more aggressive behavior than common gastric cancer because the disease progresses rapidly and metastasizes frequently in the regional lymph nodes and liver." (PMID 23382965, 2013). "Alpha-fetoprotein (AFP)-producing gastric cancer (AFPGC), represented by the production of AFP, has a more aggressive behavior than common gastric cancer." (PMID 23382965, 2013). "We entered the keywords “AFPGC” or “jia tai dan bai AND wei ai” (the equivalent Chinese phrases for α-fetoprotein AND gastric cancer using Chinese characters) and searched for clinical studies in which patients with AFP-positive GC were examined." (PMID 24083471, 2013). "Survival of patients with gastric cancer was lower with AFP and STAT3 double overexpression than with overexpression of either alone." (PMID 23382965, 2013). "Mi H, Zhao X, Yang Y: Expression of AFP in gastric carcinoma and its relationship with VEGF.Mod Oncol 2011, 19:106–108." (PMID 24083471, 2013). "Li B, Luo J, Li J: Clinical significance of α-fetoprotein (AFP) expression in gastric carcinoma patients.J Chin Physician 2007, 9:606–607." (PMID 24083471, 2013). "AFP-producing gastric cancer shows a high propensity for metastasizing to the liver and lymph nodes, and its prognosis is reported to be poorer as compared with that of non-AFP-producing gastric cancer." (PMID 21554678, 2011). "In the GI tract, an elevation of the serum AFP level was reported in 1.3% to 15% of gastric cancers." (PMID 22018031, 2011). "It has been reported that AFP-producing tumors account for about 2%-8% of all cases of gastric cancer, and that the percentage is higher among cases of advanced gastric cancer." (PMID 21554678, 2011). "The first case of a long-term (11 years) survival of AFP-producing gastric cancer with successfully resected metachronous liver metastasis and gastric remnant carcinoma has recently been reported." (PMID 20062620, 2009).
gastric cancer (continued). "Recently, glypican 3 (GPC3) has been evaluated as a sensitive marker for AFP-producing gastric carcinoma (GC) and its hepatoid component, and the authors support its usefulness for identifying this aggressive subgroup of GC." (PMID 20062620, 2009). "The reported incidence of AFP-producing gastric carcinoma has been 1.3%–15% of all gastric carcinomas." (PMID 19674468, 2009). "Why some gastric carcinomas show hepatoid differentiation and produce AFP has been the subject of some debate." (PMID 19674468, 2009). "Taken together, these findings suggested the aggressive nature of AFP-producing stomach cancer accompanied with MAGE-A10 gene expression." (PMID 18594524, 2008). "A possible role in tumorigenesis has been found in AFP-producing gastric cancer, an aggressive tumor type that lacks ATBF1." (PMID 18416817, 2008). "Of five cases with alpha fetoprotein (AFP) producing stomach cancer proved by serum concentration and immunohistochemistry, MAGE-A protein expression and MAGE-A10 mRNA expression were found in three cases (60.0%) and five cases (100%), respectively." (PMID 18594524, 2008). "AFP-producing stomach cancer is highly malignant and has a poor prognosis as the recurrent rate following curative resection is high." (PMID 18594524, 2008). "In this report, we describe a case with AFP-producing gastric cancer that responded to combination 5-FU/paclitaxel chemotherapy followed by a bi-weekly course of paclitaxel monotherapy." (PMID 17634124, 2007). "AFP-producing gastric cancers should be divided in to three subtypes: 1) hepatoid type; 2) yolk sac tumor-like type; and 3) fetal gastrointestinal type." (PMID 17634124, 2007). "We consider this rare case to be of significant value with respect to the treatment of AFP-producing gastric cancer with multiple liver metastases." (PMID 17634124, 2007). "Some investigators have reported that AFP-producing gastric cancer can be treated successfully with preoperative (i.e., neoadjuvant) combination chemotherapy with EPI, 5-FU, and leucovorin (LV)." (PMID 17634124, 2007). "FLEP chemotherapy was more effective for stage IV AFP-producing gastric cancer than for stage IV non-AFP-producing gastric cancer, and it improved the prognosis of AFP-producing gastric cancer due to downstaging." (PMID 17634124, 2007). "Nevertheless, further clinical evaluation of this regimen in advanced AFP-producing gastric cancer with liver metastases is required." (PMID 17634124, 2007). "The hepatoid type was the most common one of AFP-producing gastric cancer, and they were described as hepatoid adenocarcinoma that means primary gastric cancer that are characterized by both hepatoid differentiation and the production of AFP." (PMID 17634124, 2007). "It is likely that these biological observations reflect the aggressive clinical behavior of AFP-producing gastric cancers." (PMID 17634124, 2007). "AFP-producing gastric cancer has a high proliferative activity, weak apoptosis, and rich neovascularization." (PMID 17634124, 2007). "Many different kinds of molecular markers for the detection of peritoneal micrometastases have been described, such as conventional RT–PCR assay of CEA, keratin 19 and AFP using the peritoneal wash from gastric cancers." (PMID 14760382, 2004). "Given the paucity of prospective data in AFP-high gastric cancer, this report is hypothesis-generating and supports further evaluation of chemo-immunotherapy in larger studies." (PMID 42051505, 2026). "Among 766 gastric cancer (GC) patients, 3.3% (n=25) exhibited elevated AFP levels (>20 ng/mL)." (PMID 40485723, 2025). "AFPGC accounts for 2.7% to 5.4% of all gastric cancers, and serum AFP levels vary across cases." (PMID 40922714, 2025). "This study is innovative in two aspects: first, it validated the diagnostic value of the combined detection of CA125, AFP, and CEA for gastric cancer; second, it confirmed the close association of CA125, AFP, and CEA with the prognosis of gastric cancer patients." (PMID 40406247, 2025).
gastric cancer (continued). "Among the 35 evaluable patients, the ORR and DCR were 55.6% and 86.1%, with 12-month PFS and OS rates of 42.1% and 63.7%, respectively, confirming that AFP-producing gastric cancer may benefit from PD-1 blockade." (PMID 40999892, 2025). "Diagnostic value of serum CA125, AFP, and CEA in gastric cancer." (PMID 40406247, 2025). "However, the role of AFP as a general prognostic marker in gastric cancer beyond AFPGC remains contentious, with some studies indicating potential utility in disease monitoring, while others highlight its limited sensitivity and specificity." (PMID 40299527, 2025). "In terms of treatment, adult gastric cancer protocols may offer greater efficacy than AFP‐tumor‐specific regimens in pediatric AFPGC." (PMID 40922714, 2025). "However, many studies have shown that AFP can also be produced by various other tumors, with gastric cancer (GC) being the most common among them." (PMID 39928247, 2025). "Study showed that overexpression of AFP in gastric cancer patients significantly inhibited the infiltration of CD8+T cell, could promote liver metastasis by regulating the PTEN/AKT1/SOX5/CES1 signaling axis." (PMID 40900791, 2025). "The concept of HAS originated from AFP-producing gastric cancer (AFPGC)." (PMID 40235542, 2025). "This nomogram could assist clinicians in predicting individual patient survival probabilities and facilitate more informed treatment decisions, particularly for those with AFP-positive gastric cancer." (PMID 40485723, 2025). "However, systematic studies specifically addressing AFP-positive gastric cancer patients are sparse, with many characterized by limitations such as small sample sizes and patient heterogeneity." (PMID 40485723, 2025). "However, HAIC with 5-FU and cisplatin has shown promise as an effective and valuable treatment modality for AFP-producing gastric cancer presenting only with liver metastases after radical gastrectomy." (PMID 40538847, 2025). "Standard adult gastric cancer treatment protocols appeared more effective than AFP‐tumor‐specific regimens, suggesting they may be optimal for pediatric AFPGC as well." (PMID 40922714, 2025). "Furthermore, single-sample gene set enrichment analysis has revealed that AFP overexpression in AFP-producing gastric cancer significantly suppresses CD8+ T cell infiltration into the tumor microenvironment." (PMID 40430002, 2025). "It shares similar clinical and pathological features with AFP-producing gastric cancer." (PMID 40999892, 2025). "Furthermore, exploring the associations between AFP expression and prognosis in liver and gastric cancer patients, we found that higher level of AFP expression had a shorter overall survival time compared to those with a lower level of AFP expression." (PMID 39135041, 2024). "Because serum AFP may be the only available marker for gastric cancer cases with the GAPEP phenotype, perioperative monitoring of serum AFP level is useful for the early detection of liver metastasis relating to the GAPEP phenotype." (PMID 38355790, 2024). "AFP-producing gastric cancer has poor prognosis and is prone to liver metastasis." (PMID 38355790, 2024). "Alpha-fetoprotein-producing gastric cancer has a poor prognosis and is prone to liver metastasis." (PMID 38355790, 2024). "Alpha-fetoprotein-producing gastric cancer (AFPGC) is a highly malignant subtype of gastric cancer, but solely alpha-fetoprotein may fail to accurately predict the prognosis." (PMID 39902132, 2024). "In gastric cancer, several studies have demonstrated a close association between long-term prognosis and various tumor markers, such as CA72-4, CEA, CA19-9, CA125, and alpha fetoprotein." (PMID 38473233, 2024). "AFP-silenced gastric cancer cells exhibited significantly stronger cisplatin sensitivity." (PMID 39135041, 2024). "AFP-producing gastric cancer (AFPGC) is a rare type of gastric cancer (GC)." (PMID 37150760, 2023).
gastric cancer (continued). "The relations of high AFP and gastric cancer were widely acknowledged owing to the previous works." (PMID 36647059, 2023). "Additionally, some GA patients also had elevated AFP levels, which is called AFP-producing gastric cancer." (PMID 37538113, 2023). "It providing a reference for immunotherapy of patients with AFP-positive advanced gastric cancer." (PMID 36387141, 2022). "Previous studies have revealed that several circulating exosomal lncRNAs, such as lncRNA PCSK2–2:1 and GNAQ-6:1, are better biomarkers for distinguishing gastric cancer patients from healthy people compared to traditional diagnostic biomarkers, such as CEA and AFP." (PMID 35778697, 2022). "Healthy adult adults have very low levels of AFP, and some primary cancers can cause significant increases in this factor; therefore, it can be used to screen for tumors and other pathologies in adults, including primary HCC, and gastric cancer." (PMID 36199582, 2022). "Hence, it is recommended that physicians routinely check AFP levels in gastric cancer patients, especially if there is concern about liver metastasis." (PMID 36428707, 2022). "We concluded that gastric cancer was significantly related to gender, age, alpha fetoprotein (AFP), carcinoembryonic antigen (CEA), carbohydrate antigen 125 (CA125), carbohydrate antigen 199 (CA199), and carbohydrate antigen 242 (CA242) positive levels (P < 0.001)." (PMID 35611170, 2022). "To date, several PDX models were presented for gastric cancer covering common pathological types, alpha-fetoprotein (AFP) secretion type and human epidermal growth factor receptor 2 (HER-2)-positive gastric cancer, which provided a promising tool for translation research of gastric cancer." (PMID 36465411, 2022). "AFPGC is defined as gastric cancer with elevated serum AFP > 20 ng/mL." (PMID 36076263, 2022). "From the perspective of tumor markers, the importance coefficient of CA199, CA125 and AFP were high, and the coefficient difference between these variables was relatively small, indicating that these variables played important roles in gastric cancer screening." (PMID 36526664, 2022). "Therefore, we recommend using sAFP and AFP/GPC3/SALL4 immunohistochemistry for all cases of gastric cancer." (PMID 34706681, 2021). "It accounts for approximately 0.17%–15% of all gastric cancers, with an estimated annual incidence of 0.58–0.83 cases per 1 million individuals, and shows atypical clinical symptoms that are characterized by high serum AFP." (PMID 34956891, 2021). "In a study of exosomal miRNA, elevated serum exosomal levels of miR-19b-3p and miR-106a-5p were identified in gastric cancer patients, and their combined evaluation resulted in substantial improvements in gastric cancer diagnosis, superior to the clinically used serum biomarkers AFP and CA19-9." (PMID 34283058, 2021). "Hepatoid adenocarcinoma is the most common AFP-producing gastric carcinoma." (PMID 33956241, 2021). "Furthermore, addition of rapamycin diminished the residual activity of mTORC1 and significantly intensified the cytotoxicity of cisplatin in the gastric carcinoma cells producing alpha-fetoprotein (AFP) to be resistant to cisplatin." (PMID 33925400, 2021). "Alpha-fetoprotein producing gastric carcinomas (AFPGC) are rare and aggressive." (PMID 34168152, 2021). "High plasma miR-122 levels have been detected in AFP-producing gastric cancer." (PMID 32635415, 2020). "This study regarding AFP-producing gastric carcinoma and AFP–antibody treatment also suggested that AFP itself might up-regulate angiogenesis, and the treatment by AFP–antibody could have anti-angiogenic effects." (PMID 32850426, 2020). "Both hepatoid adenocarcinoma of stomach (HAS) and alpha-fetoprotein-positive gastric cancer (AFPGC) are rare but aggressive subtypes of gastric cancer, but few studies focus on the clinicopathologic differences and prognostic factors between them because of their rarity and histologic overlap." (PMID 31915699, 2019).
gastric cancer (continued). "However, elevated serum AFP has also been observed in multiple cancers of various other organs, and gastric cancers were the most common among these tumors." (PMID 31915699, 2019). "However, other studies indicated that a high level of serum AFP is an independent prognostic factor in gastric cancer." (PMID 30989433, 2019). "All these differences indicate that HAS may be a genetically distinct subgroup compared with GAED, although many overlapping clinicopathological features exist between the two subcategories of gastric cancer, including a solid pattern and AFP expression." (PMID 30989433, 2019). "Therefore, we next investigated the expression of pluripotency-related proteins in human AFP-producing gastric cancers." (PMID 29802314, 2018). "In this case, as with AFP-producing gastric cancers, fetal differentiation may be induced, and immunohistochemical studies showed positive results for these oncofetal proteins." (PMID 30191347, 2018). "Gastric cancer with a high level of AFP is termed α-fetoprotein–producing gastric cancer (AFPGC)." (PMID 28423604, 2017). "Not limited within GCLM, maybe triplet regimen can be tried to be used in all AFP-elevated gastric cancer in future clinical practice." (PMID 29434637, 2017). "Therefore, systemic chemotherapy became the predominant treatment method for serum AFP-elevated gastric cancer with liver metastasis (GCLM)." (PMID 29434637, 2017). "The incidence of AFP-producing gastric cancer was merely 1.3–15.0% worldwide." (PMID 29434637, 2017). "However, many studies have revealed that several other kinds of tumor can produce AFP, among which gastric cancer is the most common." (PMID 28423604, 2017). "In addition, tumor markers including CEA, CA19–9, and AFP were demonstrated to be prognostic factors for gastric cancer." (PMID 29121872, 2017). "Alpha-fetoprotein–producing gastric cancer is a relatively rare form of gastric cancer." (PMID 28423604, 2017). "The treatment of AFP-producing gastric cancer mainly includes radical surgery and chemotherapy." (PMID 27995033, 2016). "Alpha-fetoprotein (AFP)-producing gastric cancer is a relatively rare form of stomach malignancy." (PMID 27995033, 2016). "Yet, if we focus apatinib on serum AFP elevated gastric cancer patients, there are still some questions needed to be considered: First, when is the best time to use apatinib for patients with serum AFP elevation gastric cancer?" (PMID 27631210, 2016). "So, maybe, we can focus apatinib on gastric cancer patients with high serum AFP level and make further research." (PMID 27631210, 2016). "The patient was clinically diagnosed as AFP-producing gastric cancer." (PMID 27995033, 2016). "AFP-producing gastric cancer highly expresses VEGF-C, SALL4, and c-Met/HGF." (PMID 27995033, 2016). "In addition, elevated levels of preoperative tumor markers, including CEA, CA19-9, AFP, and CA125, were demonstrated to be associated with gastric cancer prognosis." (PMID 27533455, 2016). "However, some other diseases can also be related with elevated levels of AFP, gastric cancer included." (PMID 27995033, 2016). "Thirdly, whether apatinib can be used as the second-line treatment for patients with serum AFP elevated gastric cancer?" (PMID 27631210, 2016). "AFP-GC is pathologically divided into 2 types, hepatoid adenocarcinoma and nonhepatoid adenocarcinoma, including poorly/moderately/well-differentiated adenocarcinoma of common type gastric cancer and enteroblastic adenocarcinoma." (PMID 25591731, 2015). "Other serum markers associated with gastric cancer are CA50, STN, CA125, AFP, IAP, and TPA." (PMID 25884401, 2015). "Stomach HAC is the most common AFP-producing carcinoma, accounting for ~2.5–15% of gastric cancers." (PMID 24959228, 2014). "Alpha-fetoprotein (AFP)-producing gastric cancer with brain metastasis has been reported and AFP may thus be useful as a predictive factor for brain metastasis." (PMID 25411022, 2014).